SIRT2 (sirtuin 2)
Diseases named in the same sentence as SIRT2 in open-access papers (continued):
Sharing a sentence is not in itself a finding about the gene and the disease.
cancer (continued). "Recent evidence highlights the role of SIRT2 in serous ovarian carcinoma, where its reduced expression is responsible for cancer progression, promoting cell migration, invasion, lymph node metastasis, and peritoneal dissemination." (PMID 30761005, 2019). "Three compounds showed pronounced SIRT2 inhibition and antiproliferative effects against different cancer cell lines, making them promising candidates for further optimization." (PMID 31510043, 2019). "The brain-expressed X-linked 4 (BEX4) gene has been recently identified as a mediator of microtubule hyperacetylation through sirtuin 2 inhibition and is highly overexpressed in human cancers." (PMID 30367032, 2018). "SIRT2 knockout mice develop cancers in multiple organs via aurora-A and -B that direct centrosome amplification, aneuploidy, and mitotic cell death." (PMID 30081901, 2018). "Because cancer is a consequence of uncontrolled cell division and proliferation, many researchers have focused on the role of SIRT2 in tumorigenesis, as SIRT2 is involved in cell cycle progression, cellular necrosis, and cytoskeleton reorganization." (PMID 30166528, 2018). "SIRT2 has been identified as having both cancer-promoting functions (i.e., through stabilization of Myc oncoproteins in breast cancer), as well as cancer-suppressing functions (i.e., through tubulin regulation)." (PMID 29423902, 2018). "Greater P300 correlates with seminal vesicle invasion, increased Gleason Sum (4 + 3, 4 + 4, 4 + 5) demonstrates decreased SIRT2 (P = 0.02) compared to lower Gleason scores cancers." (PMID 29262808, 2017). "A progressive decrease in nuclear SIRT2 staining occurs comparing benign to cancer or metastases (p = 0.04 and p = 0.03 respectively)." (PMID 29262808, 2017). "While it is undisputed that the activity of SIRT1 is correlated to the growth of several kinds of cancer cells, the exact function of SIRT2 within cancer cells was the subject of strong controversy until recently." (PMID 28989670, 2017). "Critically, SIRT2 is itself upregulated by MYC in cancer cell lines; it constitutes a positive-feedback loop that promotes MYC-dependent transcription and oncogenesis." (PMID 28092669, 2017). "Based on our previous finding that Sirt2-/- mice develop spontaneous tumors, and a recent study showing that KRAS is acetylated in cancer cells, we aimed to determine the role of SIRT2 in KRAS-induced tumorigenesis in vivo." (PMID 27637077, 2016). "We recently showed that down-regulation of Sirtuin deacetylases 2 (SIRT2) in NSCLC increased cancer cell growth through suppressing p27." (PMID 26942878, 2016). "The authors also showed that short hairpin RNA-mediated suppression of SIRT2 expression in HCC cell lines suppressed cancer cell motility and invasiveness, by induction of regression of epithelial-mesenchymal transition." (PMID 26942878, 2016). "There are no data in the literature about the prognostic value of the combined evaluation of SIRT1 and SIRT2 protein levels in cancer patients." (PMID 25915617, 2015). "Sirtuin 2 (SIRT2) is a NAD+-dependent deacetylase that has been associated with neurodegeneration and cancer." (PMID 26407304, 2015). "In contrast to our findings, downregulation of SIRT2 protein has been reported in different malignant tumors, including lung." (PMID 25915617, 2015). "This review presents the most significant findings of sirtuins with an emphasis on SIRT1 and SIRT2 as small-molecule modulators of SIRT1 and SIRT2 and their therapeutic potential against cancer." (PMID 25486244, 2014). "This review highlights the possibility of sirtuins, especially SIRT1 and SIRT2, for cancer therapy targets, and focuses on the therapeutic potential of sirtuin modulators both in cancer prevention and treatment." (PMID 25486244, 2014). "Inhibitors of SIRT1 and SIRT2 have been proposed for treatment of cancer but are far from clinical trials." (PMID 23408731, 2013).
cancer (continued). "In rodents, SIRT2 is defined as a tumor suppressor by maintaining genome stability; however, recent studies show that SIRT2 can be a therapeutic target in cancer treatment." (PMID 23460888, 2013). "While SIRT2 down-regulation induces apoptosis, reduced expression of SIRT2 in human cancer cells have been reported." (PMID 23460888, 2013). "Inhibition of Sirt1 was shown to sensitize cells for DNA-damaging cancer therapeutics, and inhibition of Sirt1 and Sirt2 can itself decrease tumor growth." (PMID 21937767, 2011). "Sirt2 further contributes to regulation of cell cycle progression, and although details of its function seem to vary in different cancers, inhibition of Sirt2 seems to be a viable approach for destroying tumor cells." (PMID 21937767, 2011). "Here, we identify SIRT2 as a key positive regulator of PD-L1 across multiple human cancers." (PMID 42228402, 2026). "Thus, SIRT2-regulated GCLC succinylation represents an essential signaling axis for cancer cells to maintain their redox balance in coping with oxidative stress-induced ferroptosis." (PMID 40188196, 2025). "SIRT2 also plays a dual role in cancer, depending on the specific context." (PMID 39215785, 2025). "Notably, SIRT2 exhibits both oncogenic and tumor-suppressive functions across different cancer types, indicating context-specific roles in cancer progression." (PMID 39944690, 2025). "Further, SIRT2 directly impacts the cellular DNA damage response by regulating the ataxia telangiectasia-mutated and Rad3-related protein (ATR) checkpoint pathway in both cancer and normal cells." (PMID 41333420, 2025). "In some cancer types, SIRT2 plays both a tumor promoting and tumor suppressing role." (PMID 39215785, 2025). "Less characterized but important, this implicates SIRT2 inhibition as a new anti-cancer mechanism." (PMID 41425553, 2025). "Together, the data from cancer patients indicated that targeting for Fn14 ‐SIRT2‐Slug axis might be a novel strategy for the treatment of EOC." (PMID 40344622, 2025). "These evidences support the notion that cancer cells could avoid oxidative stress-induced ferroptosis through activating the SIRT2-GCLC-GSH signaling axis." (PMID 40188196, 2025). "As the disruption of the two enzyme activities could promote cancer processes, the team conceived a hybrid structure inspired by the Sirt2 and HDAC6 respective selective inhibitors." (PMID 40143119, 2025). "Taken together, there is compelling evidence to suggest that targeted inhibition of SIRT1 and SIRT2 may inhibit DNA repair and reduce the ability of cancer cells to resist oxidative stress induced by radiation." (PMID 41333420, 2025). "SIRT2 was found to shuttle between the cytoplasm and nucleus, where it deacetylates Slug, preventing its acetylation-dependent degradation and enabling it to promote cancer cell migration, invasion, and EMT." (PMID 41471349, 2025). "Isoforms such as SIRT1, SIRT2, and SIRT6 are mainly associated with tumor-suppressive activities, a function determined by their subcellular localization and the biochemical context of each cancer type." (PMID 41425553, 2025). "And, the results have shown that targeting SIRT2 significantly inhibits migration and invasion of cancer cells, indicating targeting SIRT2 may be a promising approach to treat EOC." (PMID 40344622, 2025). "Notably, a correlation between in vitro SIRT2 inhibition and cancer cell cytotoxicity was also established, although other possible modes of action against different targets should not be discounted." (PMID 40662236, 2025). "Interestingly, due to the different subcellular localization of SIRTs, SIRT1 and SIRT2 are localized in the nucleus and cytoplasm of the cell, and play diverse functions in cancer." (PMID 39479446, 2024).
cancer (continued). "The other 32 SIRT2 mutants might have gained oncogenic functions, such as promoting the expression of oncogenes, or lost other cancer-preventive functions, such as mediating HR repair and the stabilization of tumor suppressors." (PMID 38554113, 2024). "Furthermore, SIRT2 influences the metabolic profile of cancer cells by inducing the production of lactosylceramide through the upregulation of B4GALT5 beta-1,4-galactosyltransferase 5 (B4GALT5), which enhances the invasive potential of PCa cells." (PMID 39796040, 2024). "The pro-carcinogenic effects of SIRT2 are closely related to metabolic processes in cancer." (PMID 39479446, 2024). "By contrast, associations of stronger upregulation of SIRT1, SIRT2, and SIRT5 with sensitivity to dasatinib were unexpected, since previous studies had reported benefits of their downregulation or depletion in improving cancer outcomes." (PMID 38369747, 2024). "Importantly, data mining revealed that the mRNA level of SIRT2 was positively correlated with the OGG1 mRNA level in 18 of 33 different types of cancers, confirming that SIRT2 promotes OGG1 expression at the transcriptional level." (PMID 38554113, 2024). "We propose that the opposite oncogenic and tumor-suppressive roles of SIRT2 might rely on biological contexts such as the type and stage of cancer." (PMID 38554113, 2024). "Additionally, JH-T4 increased cellular fatty acylation of the Sirt2 target K-Ras4a and demonstrated cytotoxicity in multiple cancer cell lines." (PMID 38474697, 2024). "In CRPC and NEPC, SIRT2 expression is notably upregulated through the activation of the ERK1/2 signaling pathway, which is often associated with chemoresistance in cancer by enhancing cellular survival mechanisms, promoting proliferation, and inhibiting apoptosis." (PMID 39796040, 2024). "Although the controversy over whether SIRT2 is cancer-promoting or cancer-suppressing still exists, according to some reports, SIRT2 inhibitors have shown real promise in treating cancer." (PMID 38755125, 2024). "Through deacetylation, SIRT2 can prevent the growth of cancer." (PMID 39479446, 2024). "In addition to cancer development and progression, SIRT2 was proven to be involved in conferring re-sistance to cancer treatment." (PMID 36678624, 2023). "Similarly, SIRT2 maintains genome integrity in the context of carcinogen‐induced cancer models, limiting tumour growth." (PMID 38009412, 2023). "Consequently, the mutual interaction between SIRT2 and these proteins illustrates the importance of this enzyme in the cell cycle regulation and establishes a link between SIRT2 and cancer, a disease characterized by genomic instability and aberrant mitosis." (PMID 37106761, 2023). "It is conceivable that pharmacological inhibition of SIRT2 may reprogram cancer cells to augment HCC immunotherapy." (PMID 37115693, 2023). "In addition, SIRT2 expression is down- or up-regulated in different malignancies, making SIRT2 modulators interesting compounds in the search for anti-cancer agents." (PMID 37765125, 2023). "While the roles of SIRT2 are complex and might vary in different cancers, pharmaceutical inhibition of SIRT2 holds promise as a potential treatment for certain types of cancer." (PMID 38005376, 2023). "Loss of cell cycle regulation and altered cell metabolism are two imperative hallmarks of cancer; therefore, Sirt2 may represent an “Achilles’ heel” that could simultaneously affect both of these key tumorigenic phenotypes." (PMID 37628798, 2023). "Studies have shown that SIRT2 can promote various cancers through various metabolic pathways." (PMID 36101744, 2022). "We found that the SIRT2 expression level was related to different clinical covariates, including the history of neoadjuvant therapy, person neoplasm cancer status, primary therapy outcome success, ethnicity, and some other clinical characteristics in LUAD and LUSC cohorts using MEXPRESS database." (PMID 36844923, 2022).
cancer (continued). "Hypothetically, the overexpression of the APC/C substrates in human cancers may be due to the downregulated expression of SIRT2, which may result in aberrant mitotic cell division." (PMID 36291902, 2022). "Moreover, studies have found that inhibition of SIRT2 can induce apoptosis in cancer cells, having a multifaceted role in regulating autophagy." (PMID 35813508, 2022). "It was also proposed that sirtuins, especially SIRT1 and SIRT2, might play essential roles in the maintenance and differentiation of various cancer stem cells." (PMID 35326523, 2022). "In recent years, the role of SIRT2 in cancer has remained controversial, and SIRT2 acts as both an oncogene and a tumour suppressor; to a certain extent, its impact may be greater than that of SIRT1." (PMID 36101744, 2022). "In many types of cancer, SIRT-2 acts as a tumor promotor and therefore its inhibition may be beneficial." (PMID 36080416, 2022). "Moreover, LGG is the only type of cancer in which the SIRT2 expression level is higher than the paired normal tissue, while SIRT2 is lowly expressed in OV, TGCT, and UCEC based on the GEPIA database." (PMID 36844923, 2022). "Many SIRT-2 inhibitors displayed their anti-cancer activity by blocking cell proliferation." (PMID 36080416, 2022). "The expression levels of SIRT2 in multiple cancers may differ from database to database, which may depend on the underlying biological mechanisms and the data collection approaches, and also the comparison criterion might be a reason." (PMID 36844923, 2022). "It has been demonstrated that SIRT2 inhibition by TM, a potent SIRT2-specific inhibitor with a broad anticancer effect in numerous human cancer cells as well as mouse models of BC, promotes expression of the NEDD4 E3 Ubiquitin Protein Ligase for c-Myc, causing c-Myc ubiquitination and degradation." (PMID 35406775, 2022). "SIRT2 knockdown or its pharmacological inhibition inhibits cancer cell proliferation and growth." (PMID 35054489, 2022). "SIRT2 may act as an inducer or inhibitor in cancer, which may be related to cancer subtypes, subcellular localization, changes in deacetylase activity, and differences in substrate expression levels." (PMID 36344502, 2022). "This outcome may suggest that cancer cells respond to SIRT2 inhibition with an increase in its gene expression in order to restore its functionality, which is crucial for the survival of AML cells." (PMID 36289647, 2022). "Inhibition of SIRT2 expression results in the arrest of growth in many types of cancer cells." (PMID 35406775, 2022). "In this article, we mainly describe the effects of SIRT2 on cancer through metabolic pathways." (PMID 36101744, 2022). "SIRT2 is mainly distributed in the cytoplasm and is particularly important for the growth and metabolism of tumor cells, which makes SIRT2 an attractive target for cancer treatment." (PMID 35680848, 2022). "In cancer, SIRT2 can play both a tumor promoting and tumor suppressing role." (PMID 34368168, 2021). "Our data suggest that radiotherapy reduced SIRT2 level and this reduced level in soluble proteins may be useful in cancer therapy." (PMID 33705642, 2021). "Knockdown or inhibition of Sirt-2 may disrupt the metabolism of cancer cells and thus prevent the spread and growth of cancer cells." (PMID 35478872, 2021). "A direct comparison of NH4-6, which inhibits SIRT1-3, and NH4-13, which only inhibits SIRT2, showed that selective SIRT2 inhibition could be advantageous when treating cancer." (PMID 34650436, 2021). "The role of SIRT2 in the immune response beyond cancer is also an interesting question." (PMID 34155309, 2021).
cancer (continued). "Similarly, the use of SIRT2 specific inhibitor: TM (thiomyristoyl lysine compound) stimulates c-Myc ubiquitination and its degradation in various cancer cell lines depending on the sensitivity of cells to TM." (PMID 34769241, 2021). "As HeLa cells are carcinoma-derived with known aberrant regulation of cell viability, we performed similar alamarBlue assays in primary immortalised mouse embryonic fibroblasts (MEFs) derived from wildtype or Sirt2-/- mice." (PMID 34929015, 2021). "Similarly, SIRT2 enhances the stability of n-myc and c-myc oncogenes leading to cancer cell proliferation." (PMID 31973227, 2020). "The NAD-dependent histone deacetylase sirtuin 2 (SIRT2) plays critical roles in mitosis and cell cycle progression and recently was shown to suppress tumor growth and to be downregulated in several types of cancers." (PMID 31932479, 2020). "SIRT2 is widely expressed in different organs and tissues, exerting critical functions in cancer." (PMID 33207824, 2020). "A growing body of literature also suggests that SIRT2 may be a valid drug target in certain cancers." (PMID 31973227, 2020). "Overall, the crucial role of SIRT2 in mitosis regulation and genome integrity implies that its activity may have a significant effect on cancer, a disease with high genetic instability and abnormal mitosis." (PMID 33014852, 2020). "Considering that SIRT2 suppression inhibits cell cycle re-entry, SIRT2 may be a therapeutic target for cancer." (PMID 32213867, 2020). "SIRT2 has been shown to play a critical role in cancer but it is still inconsistent whether it is an oncogene or a tumor suppressor." (PMID 33207824, 2020). "Sirt2-/- mice develop gender-specific cancers in multiple organs, which indicate that SIRT2 may function as a tumor suppressor." (PMID 33061819, 2020). "Importantly, disruption of Sirt2 by siRNA or Sirt2 inhibitor significantly suppressed cancer cell growth." (PMID 31324785, 2019). "SIRT2 has been reported to reduce E-cadherin expression in mouse embryonic fibroblasts (MEFs) and was recently shown to positively regulate migration and invasion in the context of cancer." (PMID 31817470, 2019). "However, studies of SIRT2 functions in cancers have obtained contradictory results, indicating that further studies will be required to estimate the therapeutic potential of targeting SIRT2 in cancer." (PMID 30081901, 2018). "Altogether these results indicate that the inhibition of SIRT1 and SIRT2 activities by eurochevalierine may account for its cytostatic anti-cancer properties observed previously." (PMID 29401749, 2018). "Therefore, SIRT2 has been identified as a potential drug target for treatment of various neurodegenerative and inflammatory diseases and cancer." (PMID 29423902, 2018). "On the other hand, treatment with different SIRT2 inhibitors induces cancer cell apoptosis." (PMID 28061480, 2017). "The SIRT2 gene is located at chromosome 19q13.2, and has been identified in a various of cancers." (PMID 28514749, 2017). "Given that Ras proteins play critical roles in many human cancers, SIRT2, as a Ras regulator, may be an important therapeutic target for cancer, which is consistent with several recent reports." (PMID 29239724, 2017). "We hypothesized the staining pattern of SIRT2, an inhibitor of P300, would decrease given the increased hyperacetylation of H3K18Ac seen in cancer." (PMID 29262808, 2017). "Although SIRT2 play an important role in the prognosis of cancer, no study has reported that SNPs is associated with cancer." (PMID 28514749, 2017). "In diverse types of cancers, SIRT2 gene expression is downregulated or upregulated." (PMID 28445509, 2017).